ZFAS1 (ZNFX1 antisense RNA 1)
Diseases named in the same sentence as ZFAS1 in open-access papers (continued):
Sharing a sentence is not in itself a finding about the gene and the disease.
tumor (continued). "Furthermore, ZFAS1 was found to promote the progression of CRC by competitively binding miR-150-5p, which plays a tumor suppressor role in CRC by targeting VEGFA." (PMID 36545127, 2022). "Moreover, the TCGA data also showed again that ZFAS1, EBLN3P, or GAS5 was overexpressed in PCa tumor compared to adjacent normal samples." (PMID 36514044, 2022). "Besides, we found that ZFAS1 knockdown significantly reduced xenografts sizes and weights compared to control groups, but SRSF3 co-expression reversed tumor progression upon ZFAS1 knockdown." (PMID 35184675, 2022). "Moreover, we validated the overexpression of ZFAS1 in CRC tissues compared with normal tissues and found that ZFAS1 was positively correlated with tumor size and metastasis in CRC." (PMID 35036050, 2022). "Firstly, we selected several genes related to tumor metastasis through the NCBI database and literature, including SRA1, DBF4 zinc finger B (DBF4B), ZNFX1 antisense RNA 1 (ZFAS1), colorectal neoplasia differentially expressed (CRNDE), endoplasmic reticulum lectin (OS9), and others." (PMID 34011971, 2021). "Further study showed that amplified ZFAS1 could enhance HCC cell invasion and tumour metastasis in vitro and in vivo." (PMID 30288832, 2019). "Amongst them, TUG1 and linc-ROR were not detectable in plasma, ZFAS1 was significantly up-regulated in plasma of tumor patients, while GAS5 showed no significant changes." (PMID 29559565, 2018). "Thus, MALAT-1 promotes tumor growth and migration and prevents tumor cell apoptosis, linc-POU3F3 induces angiogenesis, ZFAS1 promotes proliferation and migration of cancer cells." (PMID 30211160, 2018). "When ZFAS1 is upregulated in HCC, is hypothesized to act as a sponge to decrease the concentration of miR-150, thereby upregulating ZEB1, which induces tumor cell invasion and metastasis in in vitro and animal models." (PMID 28333948, 2017). "Conversely, no statistical correlation was observed between ZFAS1 expression with gender (P = 0.91) and tumor size (P = 0.05)." (PMID 29245995, 2017). "The other ribosomal protein gene transcripts identified in mouse mammary gland to correlate with ZFAS1, i.e. RPS21, RPS24, RPL22 and RPL28, showed significant expression differences between normal and tumour samples (*P < 0.05, **P < 0.01, ***P < 0.001, ****P < 0.0001)." (PMID 27871336, 2016). "And it was reported that lncRNA ZNFX1 antisense RNA 1 (ZFAS1) could regulate the autophagy level of NPC cells through the miR-100/autophagy related 10 (ATG10) axis and the PI3K/AKT/mTOR pathway to affect tumor progression." (PMID 37069649, 2023). "The obtained data proved that exosomal ZFAS1 may up-regulate STAT3 and down-regulate miR-124 to promote the proliferation, migration and invasion of ESCC cells, inhibit their apoptosis, and then lead to occurrence and development of ESCC tumor." (PMID 31775815, 2019). "Furthermore, the upregulation of lncRNA ZFAS1 might be a predictor of LNM, advanced stage, and deeper tumor invasion." (PMID 30544408, 2018). "The role of ZFAS1 as a potential tumour suppressor gene may not be apparent in its expression in all samples in TCGA, but may be reflected in patient survival." (PMID 27871336, 2016). "To date, no studies have elucidated whether ZFAS1 modulates tumor microenvironmental dynamics—such as PD-L1 expression or T-cell infiltration—or orchestrates epigenetic reprogramming (e.g. DNA methylation, chromatin accessibility) to confer resistance to PD-1/PD-L1 inhibitors." (PMID 41450817, 2026). "In addition, there was no further study on the linking ZFAS1 expression to the tumor size." (PMID 30544408, 2018). "Tumour and non-tumour tissues in all 20 tissues analysed expressed similar levels ofYBX1,GAPDH,HPRT1,ZFAS1, andAGAP2-AS1 RNAs." (PMID 33447385, 2020).
tumor (continued). "To determine whether ZFAS1 expression was different between tumor tissues and adjacent non-cancerous tissues, we examined 50 pairs of human ESCC samples from the Third People's Hospital of Yancheng and analyzed lncRNA ZFAS1 expression by qRT-PCR." (PMID 28938617, 2017).
cancer (101 papers, 2016 to 2026). A tumor composed of atypical neoplastic, often pleomorphic cells that invade other tissues. "Considering the ZFAS1 expression pattern, it also has the potential to be a diagnostic or prognostic marker in various cancers." (PMID 38856786, 2024). "In this review, we summarized recent progression regarding study of the functions and underlying mechanisms of ZFAS1 in the occurrence and development of various cancers." (PMID 30288832, 2019). "Many studies have shown that the expression of long noncoding RNA ZFAS1 has increased in cancers, and some scholars have linked ZFAS1 to the exosomes." (PMID 29552328, 2018). "The clinical studies showing that the upregulation of ZFAS1 expression is associated with poor prognosis in different types of cancer." (PMID 30544408, 2018). "Funnel plot analysis was performed to evaluate publication bias for the association between ZFAS1 expression and OS in cancer patients.in the study." (PMID 29245995, 2017). "Meta-analysis of those studies revealed that high ZFAS1 expression level was positively associated with poor OS in human cancer (HR: 1.87, 95% CI: 1.38-2.36, p< 0.001)." (PMID 28977885, 2017). "Our results demonstrated that increased ZFAS1 expression was significantly associated with poor OS in cancer patients (HR = 2.13, 95% CI = 1.71–2.65, P < 0.001)." (PMID 29245995, 2017). "Increased ZFAS1 expression has been associated with malignant progression, metastasis, and poor prognosis in several types of cancer." (PMID 29163829, 2017). "Based on the analysis results, we found that increased ZFAS1 expression was significantly associated with poor OS in cancer patients." (PMID 29245995, 2017). "All included articles investigated the association between ZFAS1 expression and OS with a total of 978 cancer patients." (PMID 28977885, 2017). "In summary, we have described the expression patterns of ZFAS1 in different cancer cell lines and its association with ribosomes (page 8-10)." (PMID 27871336, 2016). "Among these, lncRNA ZFAS1 has been implicated in oncogenic roles in multiple cancer types." (PMID 39001904, 2024). "We expected that the current review could fill the current scientific gaps in the ZFAS1-related cancer causative mechanisms and improve available biomarkers." (PMID 38856786, 2024). "Therefore, it has been suggested that ZFAS1 can be considered as a diagnostic and prognostic biomarker in this cancer." (PMID 38743146, 2024). "ZFAS1, another feature of this subpopulation, is associated with cancer progression and metastasis." (PMID 36598637, 2023). "ZFAS1 is a newly identified and characterized lncRNA linked to a variety of cancers." (PMID 35184675, 2022). "Whether ZFAS1 could regulate underlying targets expression through other mechanisms in cancer cells is undermined." (PMID 27246976, 2017). "The mechanisms responsible for the association between high ZFAS1 expression and poor survival in cancer patients remain unclear." (PMID 29163829, 2017). "The expression of ZFAS1 also reported to be positively associated with clinical outcome and it might be served as a promising prognostic marker in certain cancers." (PMID 28977885, 2017). "In addition, no systematic review or meta-analysis has been performed to assess the association between ZFAS1 expression and the prognosis of patients with cancers." (PMID 29245995, 2017). "While this comprehensive analysis strongly supports ZFAS1 as a pan-cancer prognostic biomarker, specific subgroup findings for HCC within this study warrant careful interpretation." (PMID 41450817, 2026). "Previously, it is highlighted the role of lncRNAs in cancer progression and drug resistance, but the specific involvement of ZFAS1 in CML resistance mechanisms was not well understood before this study." (PMID 40697388, 2025).
cancer (continued). "We also used bioinformatic webtools for analyzing the potential miRNA targets of ZFAS1 and its role in survival of cancer patients along with their role in various biological functions and pathways." (PMID 40109869, 2025). "Recently, we and others have demonstrated the involvement of Zinc Finger Antisense 1 (ZFAS1) in cancer development." (PMID 40109869, 2025). "In this study, we have discussed the mechanistic and regulatory roles of ZFAS1 in modulating the hallmarks of cancer and cellular phenotypes, including proliferation, invasion, epithelial-to-mesenchymal transition (EMT) and metastasis through sponging." (PMID 40109869, 2025). "The current findings regarding the involvement of ZFAS1 in IM resistance in CML are consistent with these previous reports and further underscore the therapeutic potential of targeting ZFAS1 in cancer treatment." (PMID 40697388, 2025). "Zinc finger antisense 1 (ZFAS1) has gained recognition as a key oncogenic driver, playing a significant role in the progression of various cancers." (PMID 41150811, 2025). "ZNFX1 Antisense RNA 1 (ZFAS1) functions as an oncogenic lncRNA across various cancer types and has recently been known for its role in suppressing ferroptosis by regulating the miR-150/AIFM2 axis in HCC." (PMID 40789840, 2025). "We have also highlighted different signaling pathways, including molecules such as STAT3, SKA1, LPAR1 and Wnt β-catenin and their involvement in cancer development through the ZFAS1/miRNAs/mRNAs axis." (PMID 40109869, 2025). "ZFAS1 is notably overexpressed in a range of cancers, including colorectal cancer (CRC), colon cancer, osteosarcoma, and GC, indicating its possible role as a universal marker for tumorigenesis." (PMID 39335515, 2024). "Higher levels of ZFAS1 lead to enhanced cancer cell motility, presumably due to an increase in reactive oxygen species." (PMID 39333489, 2024). "Increasing evidences have shown that ZFAS1 promote the initiation and development of multiple human cancers." (PMID 39296014, 2024). "In prostate cancer, knocking down ZFAS1 suppresses the migration and invasion of these cancer cells by inhibiting EMT." (PMID 36770654, 2023). "The existing studies focus on the involvement of ZFAS1 in the multiplication and metastasis of cancer cells by regulating miRNA-mediated pathways, while herein, we reveal a novel role of ZFAS1 and the potential molecule mechanism in PC." (PMID 35846429, 2022). "Taken together, these findings suggest that ZFAS1 plays a carcinogenic role in various human cancers and that the ZFAS1/hsa-miR-642a-5p/MACC1 axis constitutes the potential regulatory pathway that promotes the progression of COAD." (PMID 36545127, 2022). "ZNFX1 antisense RNA 1 (ZFAS1) is a newly discovered lncRNA that plays an oncogenic role in various cancers." (PMID 35184675, 2022). "One lncRNA module was confirmed to be associated with cancer metastasis, and nine hub lncRNAs, namely FTX, AC005261.1, NORAD, LINC01578, AC004542.2, ZFAS1, EBLN3P, THUMPD3-AS1, and GAS5, were discovered." (PMID 36514044, 2022). "Subsequent studies, however, report that ZFAS1 exerts an opposite function during the progression of most cancer types." (PMID 35846429, 2022). "ZFAS1 was identified as a novel lncRNA that has potential functions in human cancer pathological and physiological processes." (PMID 35112985, 2022). "Among all the cancer associated long non-coding genes reported (, Lnc2Cancer v3.0), we identified mutations of MALAT1, HOTAIR and ZFAS1 in these cell line models." (PMID 36153537, 2022). "Long non-coding RNA (lncRNA) ZFAS1 (zinc finger antisense 1) was demonstrated to play critical roles in various cancer progression." (PMID 35112985, 2022). "Our study verified the cancer-promoting effect of ZFAS1 in NPC and explained part of the reason for its upregulation." (PMID 34980191, 2022). "ZFAS1 partakes in the pathogenesis of diverse human disorders, including in neurodegenerative disorders, immune responses, and cancer." (PMID 36092160, 2022).
cancer (continued). "In short, our study verified the cancer-promoting effect of ZFAS1 in NPC and explained part of the reason for its upregulation." (PMID 34980191, 2022). "LncRNA ZFAS1 is highly expressed in the heart and is a regulator of organ development, cancer growth and metastasis, apoptosis and cell cycle regulation." (PMID 36240130, 2022). "To investigate the effect of ZFAS1 on CRC cells, we first examined the endogenous expression levels of ZFAS1 in various cancer cell lines by qRT-PCR." (PMID 35036050, 2022). "LncRNA ZFAS1 has been observed to express significantly up-regulated in cancer, and the up-regulated ZFAS1 promoted the migration and invasion of cancer cells." (PMID 33776780, 2021). "Despite the emerging data regarding the functions of ZFAS1 in various cancers, the epigenetic regulation network or function of an m6A reader such as the IMP1/2/3 family has not been reported, especially in CRC." (PMID 34743750, 2021). "Upregulation of the lncRNA ZNFX1 antisense RNA 1 (ZFAS1) has been initially observed in cancers promoting cell migration and invasion." (PMID 32674342, 2020). "In contrast in other solid tumors, ZFAS1 acted as an oncogene to promote the development and progression of cancers such as HCC, NSCLC, etc." (PMID 33202381, 2020). "The results showed that ZFAS1 was significantly more highly expressed in the cancer tissue samples than in the normal tissue samples and existed in both the cytoplasm and the nucleus." (PMID 32550827, 2020). "In accordance with previous introductions, ZFAS1 serves as an oncogenic lncRNA in several human carcinomas." (PMID 32744323, 2020). "More importantly, ZFAS1 promoted cancer cell migration and ROS production in HCCs to participate in tumorigenesis." (PMID 31781169, 2019). "The results showed that ZFAS1 expression was significantly elevated in cancer tissues in agreement with the microarray data (P = 1.6e−05, paired Wilcoxon rank sum test)." (PMID 31781169, 2019). "According to the database (cBioportal and UALCAN), the expression of ZFAS1 was significantly up-regulated in cancer samples of HNSCC patients compared to normal tissue (median expression of 226.109 vs. 175.467 transcripts per million; p = 2.24 × 10−14)." (PMID 31010087, 2019). "The significant differences between expression levels of ZFAS1 were observed in patients with various cancer stage (p = 0.0091) and T-stage (p = 0.0169)." (PMID 31010087, 2019). "Zfas1 is an lncRNA that has recently been reported to function as a potential oncogene by promoting cell proliferation and metastasis in several human cancers." (PMID 31231466, 2019). "Compared to GAS5 and ZFAS1, the role of miR-940 is less clear and appears to be different depending on the type of cancer." (PMID 29416676, 2018). "All included articles evaluated the relationship between the expression levels of ZFAS1 and survival, or the range of pathological features in cancer patients." (PMID 30544408, 2018). "Long non-coding RNA (lncRNA) ZFAS1 (zinc finger antisense 1) has been suggested to have an oncogenic role in the tumorigenesis of human malignant tumors." (PMID 29678899, 2018). "Further subgroup analysis revealed that ZFAS1 overexpression was significantly correlated with poor OS in different cancer types, HR obtain methods and sample sizes." (PMID 30544408, 2018). "In the present paper, we included 8 studies, 820 cancer patients and assessed the relationship between the expression level of ZFAS1 and the prognosis of tumors." (PMID 30544408, 2018). "An increasing number of studies have recently highlighted the role of zinc finger antisense 1(ZFAS1) as a prognostic marker in cancers." (PMID 30544408, 2018). "Recent studies have demonstrated that ZFAS1 was overexpressed in various cancer tissues and cell lines, and promoted the cancer progression through affecting the phenotypes of cancer cells and molecular pathways." (PMID 30186041, 2018).
cancer (continued). "The present review summarizes the current studies of regulation mechanisms and functions of ZFAS1 in the initiation and progression of human cancers." (PMID 30186041, 2018). "In this review, we provide an overview of current evidence concerning the role and potential clinical utilities of ZFAS1 in human cancers." (PMID 30186041, 2018). "ZFAS1 has been described as being upregulated in different cancer types and is involved in cell apoptosis and cell cycle control." (PMID 30087896, 2018). "Many studies confirmed that the expression of ZFAS1 is up-regulated in cancers and proved that it can compete with miR-150 as ceRNA; further, the expression of miR-150 can inhibit ZFAS1." (PMID 29552328, 2018). "Another lncRNA Zinc finger antisense 1 (ZFAS1) is reported to promote cancer progression in some cancers." (PMID 29190895, 2017). "Long noncoding RNA ZFAS1 has been identified as a crucial role in the tumorigenesis of malignant tumors." (PMID 29245995, 2017). "In conclusion, upregulation of lncRNA ZFAS1 was associated with higher positive rate of LNM, more advanced clinical stage and poorer OS in cancer patients." (PMID 28977885, 2017). "Located on the antisense strand of the Znfx1 promoter region, lncRNA ZFAS1 suggested up-regulated tumorigenesis and advanced cancer progression." (PMID 28977885, 2017). "This meta-analysis was conducted to identify the potential value of ZFAS1 as a biomarker for cancer prognosis." (PMID 29137442, 2017). "Further studies exploring the relationship between LNM and ZFAS1 expression are required to verify its clinical prognostic value in human cancers." (PMID 29137442, 2017). "Our meta-analysis showed that overexpression of ZFAS1 was correlated with unfavorable clinical outcomes in cancer patients." (PMID 28977885, 2017). "Although ZFAS1 has been widely reported to play an important role in the development and progression of many types of cancer, the expression and prognostic value of ZFAS1 in ESCC are still not clear." (PMID 28938617, 2017). "More importantly, the dysregulation of ZFAS1 was closely related to cell cycle control and apoptosis of cancer cells." (PMID 29245995, 2017). "Expression of ZFAS1, a newly identified long noncoding RNA (lncRNA), is dysregulated in several types of cancer." (PMID 29163829, 2017). "Dysregulation of long non-coding RNA zinc finger antisense 1 (ZFAS1) has been reported in many types of cancers." (PMID 28977885, 2017). "Our results revealed that high ZFAS1 expression predicted poor OS in various cancers (pooled HR: 1.94, 95% CI: 1.41–2.47, P < 0.001; fixed-effect)." (PMID 29137442, 2017). "Although the roles of ZFAS1 in cancers are complex and still unclear, some research results have been obtained." (PMID 28977885, 2017). "Our work demonstrated for the first time that the expression of ZFAS1 in ESCC was significantly higher than that in normal para-carcinoma tissue and that ZFAS1 expression is closely related to the ESCC histological grade." (PMID 28938617, 2017). "In this study, the expression of fourteen cancer related lncRNAs were investigated in paired tissues of 66 patients with GC, Realtime RT-PCR revealed that ZFAS1 was significantly upregulated." (PMID 27654478, 2016). "More importantly, expression of ZFAS1 is upregulated in un-captured cells as well, indicating ZFAS1 is enriched in mesenchymal type of cancer cells." (PMID 27654478, 2016). "In addition, ZFAS1 has a significant impact on regulating the proteins associated with EMT, a process that is critical for the invasion and spread of cancer cells." (PMID 41459628, 2026). "In conclusion, this review comprehensively summarizes the latest advancements in understanding the regulatory relationships among ZFAS1, miRNAs, and mRNAs, emphasizing their collective role in cancer development to propose innovative avenues for cancer treatment." (PMID 40109869, 2025).